LOXL1 (lysyl oxidase like 1)
Diseases named in the same sentence as LOXL1 in open-access papers (continued):
Sharing a sentence is not in itself a finding about the gene and the disease.
glaucoma (continued). "Regulation of LOXL1 by hsa-miR-335-5p has not been reported in glaucoma so far but has previously been reported in breast cancer tissue using microarrays so this may be a downstream regulatory effect." (PMID 39883689, 2025). "While Lysyl oxidase homolog 1 (LOXL1) is deemed necessary for disease pathogenesis, it is now understood that LOXL1 alone does not explain the preferential geographical distribution or the differential role of different genes in disease pathogenesis or glaucoma onset in different ethnic populations." (PMID 34943956, 2021). "In addition, we identified several transcriptional targets of GLIS1 in TM cells that previously have been implicated in TM-related functions, IOP homeostasis, and ocular hypertension/glaucoma, including MYOC, ADAMTS10, LTBP2, LOXL1, TGFBR3, CYP1B1, and EFEMP15,28,43,44." (PMID 34385434, 2021). "In our population, we suggest that the R141L allele of LOXL1 may contribute to XFG onset independently rather than through IOP elevation and subsequent glaucoma." (PMID 23687437, 2013). "In fifteen senile cataract patients without glaucoma and fifteen patients with coexisting XFG and cataract, capsulorhexis specimen of the anterior lens capsule was used to evaluate LOXL1 gene transcripts by Real-Time PCR technique." (PMID 31850260, 2019). "Signal quantification yielded differences for LOXL1 between XFS and POAG or young no glaucoma controls, which were small and non-statistically significant." (PMID 27391778, 2016). "In the present study, the allelic and genotypic frequencies of the three LOXL1 SNPs in the two XFS sub-phenotypes, i.e, XFS without glaucoma and XFG, were similar and showed no statistical significance." (PMID 22128228, 2011). "Interestingly, samples from patients with XFS who had not (yet) developed glaucoma had noticeably less FBN1, LOXL1, and LEFTY2 than samples from patients with XFG." (PMID 34964803, 2021). "In contrast to the invariance of LOXL1, Fibulin-5 expression in the XFS-TFs was 7.0-fold (p = 0.02) and 10.8-fold +/- 1.0 (p = 0.03) higher than in the POAG or young no glaucoma controls, respectively." (PMID 27391778, 2016). "Based our results, we suggest that the LOXL1 gene may contribute independently to the onset of XFG rather than through IOP elevation and subsequent glaucoma." (PMID 23687437, 2013).
pelvic organ prolapse (16 papers, 2008 to 2025). Abnormal descent of a pelvic organ resulting in the protrusion of the organ beyond its normal anatomical confines. "Homozygosity for Agpat1 or Cacna1a mutations led to early lethality; homozygosity for Loxl1 mutations led to pelvic organ prolapse, preventing aging." (PMID 38770563, 2024). "Loxl1 KO mice 13, 14 have been used to demonstrate that Loxl1 deficiency leads to abnormal elastin regulation and subsequently leads to pelvic organ prolapse, flabby skin and bullae." (PMID 34105806, 2021). "The present study aimed to investigate new clinical significance and detailed mechanism of pelvic organ prolapse by comparing the structural, functional and molecular dysfunctions of pelvic organ prolapse in patient and Loxl1 deficient mice." (PMID 34923484, 2021). "Reportedly, the loss of LOXL1 function leads to pelvic organ prolapse 10 and exfoliation syndrome glaucoma." (PMID 34105806, 2021). "In previous studies, mice deficient in the LOXL1 gene showed reduced elastin content in multiple tissues leading to pelvic organ prolapse, emphysematous changes, and vascular abnormalities." (PMID 23441117, 2013). "LOXL1‐deficient mice are more likely to develop pelvic organ prolapse." (PMID 35152572, 2022). "To answer this question, we compared the structural and functional dysfunctions of pelvic organ prolapse in patient and Loxl1 deficient mice, and use RNA-seq to resolve the molecular underpinnings of POP at high resolution, analyzing the transcriptomes of both human and mice samples." (PMID 34923484, 2021). "However, the function of LOXL1 differs from that of LOX, and LOXL1-deficient mice display pelvic organ prolapse, enlarged airspaces in the lungs, loose skin, and vascular abnormalities with concomitant tropoelastin accumulation." (PMID 27645581, 2016). "Results obtained in our laboratories, together with the phenotype of lysyl oxidase-like 1 (Loxl1) null mice, have led us to propose that pelvic organ prolapse (POP) is caused by altered balance between matrix synthesis, particularly elastic fibers, and protease activation." (PMID 23437119, 2013). "The downregulation of LOXL1 expression resulted in the inability of mice to synthesize elastic fibers normally after childbirth, leading to postnatal pelvic organ prolapse and concomitant pro-elastin accumulation." (PMID 38217541, 2024). "Previous studies using LOXL1-knockout mice (Loxl1−/−) revealed characteristic findings of elastic fiber disorder, such as pelvic organ prolapse (POP) and laxity of the skin, which established Loxl1−/− mice as a rodent model for investigating elastic fiber maintenance and homeostasis." (PMID 41009782, 2025). "In addition to both genders suffering from increased rectal prolapse with age, it was reported that Loxl1−/− female mice on a mixed background display pelvic organ prolapse 2 days postpartum, with retraction at day 14; but with permanent damage to the pelvic floor." (PMID 37905384, 2023). "We found that the N6 BL/6 mice were 98.6% BL/6 by DartMouseTM genotyping services and presented with pelvic organ prolapse by 2 months of age, whereas the 50/50 and 129S Loxl1−/− mice did not." (PMID 37905384, 2023). "Mice lacking LOXL1 display tropoelastin accumulation in multiple tissues, which leads to pelvic organ prolapse, emphysematous changes, and vascular abnormalities." (PMID 18483563, 2008).
glioma (15 papers, 2020 to 2026). A benign or malignant brain and spinal cord tumor that arises from glial cells (astrocytes, oligodendrocytes, ependymal cells). "LOXL1 increases aggressiveness of gliomas by affecting the anti-apoptotic ability of Wnt/β-linked protein signaling." (PMID 36825022, 2023). "The genes Lysyl Oxidase Like 1 (LOXL1) and Insulin Like Growth Factor Binding Protein 6 (IGFBP6) were consistently selected and linked to glioma survival, emphasising their clinical significance." (PMID 40428295, 2025). "The expression of Loxl1 is significantly related to the antiapoptotic effects and migration of glioma cells." (PMID 38978755, 2024). "Consistent with our results, previous studies have indicated a similar prognostic role for Loxl1 in glioma using a single Kaplan‒Meier analysis." (PMID 38978755, 2024). "LOXL1 accelerates the proliferation of glioma cells by modulating the Wnt/β-catenin signalling pathway." (PMID 39286023, 2024). "High Loxl1 is related to glioma cell apoptosis and migration via Wnt/beta-catenin signaling or stabilizing BAG2." (PMID 38978755, 2024). "The number of invasive glioma cells in the Transwell assay also decreased significantly after shLoxl1 knockdown, confirming that Loxl1 contributes to the invasion of glioma cells." (PMID 38978755, 2024). "It was reported that LOXL1 was related to the progression of various tumors, such as glioma, gastric cancer, colorectal cancer, pancreatic ductal adenocarcinoma (PDAC)." (PMID 37189708, 2023). "Among these six genes, ANG, IL1A, LOXL1, LOXL2, and STEAP3 played risk roles in the survival of glioma patients (HR > 1), while F5 was a potential protective factor (HR < 1)." (PMID 37891828, 2023). "The functions of LOXL1 in promoting glioma cell survival and inhibiting apoptosis were studied by gain- and loss-of-function experiments in cells and animals." (PMID 32424143, 2020). "We examined LOXL1 levels in blood samples (blood LOXL1) from 21 patients with glioma and divided them into two groups according to the levels of secreted LOXL1." (PMID 32424143, 2020). "Clinically, the patients with higher LOXL1 levels in their blood had much more abundant BAG2 protein levels in glioma tissues." (PMID 32424143, 2020). "As LOXL1 showed more significance in glioma progression, we tested LOXL1 expression in U87 and LN18 cells, and then used U87 cells as the parent cell line for forced LOXL1 expression (U87-LOXL1) and LN18 cells for LOXL1 knockdown (LN18-shLOXL1)." (PMID 32424143, 2020). "In this study, we found that LOX family proteins, especially LOXL1, can protect glioma cells from anoikis and IR stresses, rendering cells resistant to apoptosis." (PMID 32424143, 2020). "Conclusively, LOXL1 functions as an important mediator that increases the antiapoptotic capacity of tumor cells, and approaches targeting LOXL1 represent a potential strategy for treating glioma." (PMID 32424143, 2020). "We measured the mRNA expression of CEBPA and LOXL1 in 21 glioma specimens to determine the clinical relevance of our finding that LOXL1 was upregulated by CEBPA." (PMID 32424143, 2020). "LOXL1 activates Wnt/beta-catenin signaling to accelerate cell proliferation and cell growth in glioma." (PMID 32424143, 2020). "LOXL1 was found to prevent the ubiquitination of BAG2 in glioma and stabilize BAG2." (PMID 40426862, 2025). "Furthermore, the expression of LOX family members LOXL1 and LOXL2 in gliomas is also associated with tumor progression and poor prognosis." (PMID 40270974, 2025). "LOXL1 and IGFBP6 have already been associated with glioma survival in the literature." (PMID 40428295, 2025). "Through single-cell sequencing analysis, the roles of Loxl1 in the TME of glioma could be further explored." (PMID 38978755, 2024). "The expression of Loxl1 in glioma cells of GBM tissues could help us understand its functional state." (PMID 38978755, 2024).
glioma (continued). "Moreover, based on our scRNA-seq analysis, we confirmed that Loxl1 expression was closely related to glioma invasion in vitro." (PMID 38978755, 2024). "However, it is still elusive how LOXL1 is upregulated and exerts antiapoptotic function by directly forming an axis with other proteins during glioma progression." (PMID 32424143, 2020). "LOXs are secreted extracellularly to remodel the ECM and are soluble in blood, suggesting that the LOXL1 level in blood may represent a potential indicator for glioma cell survival following TMZ and IR treatment." (PMID 32424143, 2020). "Notably, patients with higher levels of LOXL1 in their blood had higher protein levels of BAG2 in their glioma tissues." (PMID 32424143, 2020). "LOXL1 was expressed at a two-fold higher level in GBM than in LGG at the mRNA level, suggesting that LOXL1 may act as a risk factor for glioma progression." (PMID 32424143, 2020). "In detail, LOXL1 is upregulated by the VEGFR-Src-CEBPA axis in suspended glioma cells, and LOXL1 and BAG2 proteins can interact in glioma cells, preventing BAG2-K186 ubiquitylation depending on LOXL1 enzymatic activity and stabilizing BAG2 to ultimately promote cell survival." (PMID 32424143, 2020). "Therefore, PI/Annexin V double-staining was performed to assess the ability of LOXL1 to promote glioma cell resistance to apoptosis." (PMID 32424143, 2020). "However, the role of Loxl1 is still unclear in glioma cell invasion." (PMID 38978755, 2024). "Our data suggest that LOXL1 can be a potential biomarker for guiding the clinical treatment of glioma, and the development of new drugs targeting LOXL1 may improve the curative efficacy and prolong survival in glioma patients." (PMID 32424143, 2020). "Also, LOXL1 could play an aggressive role in glioma through its antiapoptotic capacity via Wnt/beta-catenin signaling." (PMID 32424143, 2020). "In addition, blood LOXL1 levels can be used as a biomarker to monitor glioma progression." (PMID 32424143, 2020). "Finally, in clinical practice, the LOXL1 level in patient blood could indicate glioma progression, suggesting that LOXL1 acts not only as a potential target but also as a biomarker of gliomagenesis." (PMID 32424143, 2020). "The results indicated that members of the LOX family, including LOX, LOXL1, LOXL2, LOXL3, and LOXL4, exhibited high expression levels in glioma cells in comparison to normal human glial cell lines Heb as well as glioblastoma cell lines T98G and LN-229." (PMID 40270974, 2025). "For instance, LOXL1 and BAG2 proteins can interact in glioma cells, preventing BAG2-K186 ubiquitylation depending on LOXL1 enzymatic activity and stabilizing BAG2 to ultimately promote cell survival." (PMID 36593950, 2023). "Considering some previous investigations illustrating that LOXs, especially, LOX, LOXL1, and LOXL4 are closely associated with immunity, finally contributing to tumor progression, we would like to explore whether LOXs expressions were correlated with glioma immunity." (PMID 36160460, 2022). "The experimental results in our present work demonstrated the elevations of LOX, LOXL1, LOXL2, and LOXL3 in various glioma cell lines." (PMID 36160460, 2022). "Regarding the roles of LOXL1-4 in the glioma, LOXL1 is also demonstrated to exhibit antiapoptotic activity and promote glioma cell proliferation while the facilitation of cell invasion for LOXL3 is observed in glioma cell line U87MG." (PMID 36160460, 2022). "Experimental results revealed that expressions of LOX, LOXL1, LOXL2, and LOXL3 were higher in glioma cell lines at mRNA and protein levels." (PMID 36160460, 2022). "LOXL1, which belongs to the LOX family, has been shown to protect glioma cells against apoptosis and promote glioma development." (PMID 36292695, 2022). "We narrowed down 21 glioma specimens to 14 by selecting the samples with a better correlation between CEBPA and LOXL1 gene expression." (PMID 32424143, 2020).
glioma (continued). "The expression levels of LOXL1 and BAG2 are positively correlated (R = 0.42) in glioma and the correlation R value ranks fourth in all the 33 tumor types of TCGA." (PMID 32424143, 2020). "Notably, genes such as LOXL1, IGFBP6, TNFRSF18 and MMP19, identified by both methods, have established links to glioma survival." (PMID 40428295, 2025). "Additionally, we explored the roles of Loxl1 in tumor immune infiltrates and first validated the invasive role of Loxl1 in the progression of GBM, revealing potential intervention targets for glioma treatment." (PMID 38978755, 2024). "In the present study, a progressive increase in levels of LOX, LOXL1, and LOXL3 expression was observed for LGG-IDHmut, LGG-IDHwt, and GBM in the TCGA glioma RNAseq dataset, suggesting their role in determining ECM composition and stiffness enhancement in these phenotypes." (PMID 36076905, 2022). "The results shown in CGGA-325 dataset revealed that the glioma patients with the high levels of all members of LOX family including LOX, LOXL1, LOXL2, LOXL3, and LOXL4 displayed poor prognosis with the MST of only 34.3, 31, 31, 35.3, and 34.8 months, respectively." (PMID 36160460, 2022). "Additionally, experimental results also revealed that expressions of LOX, LOXL1, LOXL2, and LOXL3 were higher in glioma cell lines (T98G and A172) at mRNA and protein levels compared with the normal astrocyte HEB." (PMID 36160460, 2022). "Finally, RT-qPCR and Western blot analysis were carried out to validate the mRNA and protein levels of LOXs including LOX, LOXL1, LOXL2, LOXL3, and LOXL4 in glioma cells (T98G and A172) and the normal cell line (HEB)." (PMID 36160460, 2022). "The results indicated that the mRNA and protein expressions of LOX, LOXL1, LOXL2, and LOXL3 were significantly upregulated in these glioma cells than in HEB cell line while the expressions of LOXL4 at mRNA and protein level were not determined in these cell lines (data not shown)." (PMID 36160460, 2022). "Patients with recurrent glioma also showed higher LOX family gene expression, especially LOXL1." (PMID 32424143, 2020). "In the present study, under nonadherent conditions, the VEGFR/Src axis in glioma cells activates the transcription of the LOXL1 gene by increasing the binding of CEBPA to its promoter region." (PMID 32424143, 2020). "We surmise that the VEGFR-Src-CEBPA axis is important for upregulating LOXL1 expression in nonadherent cells, which in turn confers glioma cells the ability to resist apoptosis." (PMID 32424143, 2020). "Left panel, LOXL1 specially implicates glioma but no other tumors." (PMID 32424143, 2020). "Another study found that LOXL1 stabilizes the co-protein BAG2 by blocking K186 ubiquitination, which enables glioma cells to resist apoptosis under non-adherent conditions." (PMID 36825022, 2023). "In our study, LOXL1 stabilized BAG2 by blocking K186 ubiquitination, rendering glioma cells resistant to apoptosis in nonadherent conditions." (PMID 32424143, 2020).